CDK2 (cyclin dependent kinase 2)
Diseases named in the same sentence as CDK2 in open-access papers (continued):
Sharing a sentence is not in itself a finding about the gene and the disease.
infection (38 papers, 2009 to 2026). The state of being infected such as from the introduction of a foreign agent such as serum, vaccine, antigenic substance or organism. "GSEA results demonstrated that CDK2 is associated with the top 5 downregulated and upregulated pathway related to metabolism, infection, and biosynthesis of nucleotide sugars in HF, and genetic regulation, cell signaling and transport in KF." (PMID 39351221, 2024). "We cannot exclude that endogenous cyclin E in A549 cells may also interact with CDK2; however, we observed that the increased CDK2 in the cyclin E/CDK2 immunocomplexes was associated with cyclin EL induction after infection with replication-competent Adwt and Adhz63." (PMID 23437375, 2013). "Meanwhile, specific qPCR and immunoblot analysis to validate this finding in zebrafish tissues, which demonstrated that the cdk2 transcript level was significantly increased upon SVCV infection." (PMID 41532831, 2026). "Fish cdk2 was significantly increased upon infection with fish viruses CyHV-2 or SVCV in Carassius auratus gibelio, Danio rerio, and Pimephales promelas, compared to human cdk2, indicating that fish CDK2 is involved in the host’s antiviral response." (PMID 41532831, 2026). "As a positive control, proteasome inhibition increased the abundance of Cdk2, which is upregulated during a BKPyV infection and degraded throughout the cell cycle." (PMID 39636788, 2024). "We find that SIRT2 interacts with and modulates the acetylation level of cell cycle proteins during infection, including the cyclin-dependent kinase 2 (CDK2)." (PMID 37916830, 2023). "Based on our cell cycle profiling results, our identification of a SIRT2-CDK2 interaction at early time points of infection, and increased CDK2 K6 acetylation following SIRT2 inhibition, we therefore focused our follow-up investigations on CDK2." (PMID 37916830, 2023). "In line with the high cyclin E expression seen in MCF7/pR cells, basal phospho-CDK2 levels were markedly increased relative to MCF7/pS cells, and OAdmCherry infection resulted only in a minor increase in phospho-CDK2." (PMID 31100952, 2019). "First, we confirmed downregulation of cyclin E and examined downstream T160 phosphorylation of CDK2 after OAdmCherry infection in cyclin E siRNA-transfected cells." (PMID 31100952, 2019). "To verify this prediction, we tested the CDK1/CDK2 inhibitor BMS-265246 for its ability to restrict HIV-1ΔEnv-GFP/VSVG infection." (PMID 29764952, 2018). "The expression of CDK2 and cyclinE1 was decreased after 12 h post-infection, and the expression of cyclinB1 and CDK1 was decreased by CVA6 infection at all time point tested (last six rows)." (PMID 30159255, 2018). "Experimental infections were performed, using HEp-2 and HEp-dnERK cells to directly correlate the regulation of cyclin E and CDK2 levels with the inhibition of ERK1 activity." (PMID 28835716, 2017). "Since we had observed up regulation of cyclin E transcripts even at late time post infection (24 h) we analyzed also the transcripts levels of CDK2 cellular gene related to cyclin E function." (PMID 28835716, 2017). "Immunoblotting showed that both shRNAs lowered CDK2 protein level by 80% ± 5% and the level of active, phosphorylated CDK2 (Thr160) by 70% ± 0.8% 48 h after infection compared to podocytes infected with viruses carrying the empty vector shRNA." (PMID 26876672, 2016).
infection (continued). "The expression of p21WAF/CIP1 was dramatically downregulated with time after infection, whereas expression of CDK2, a gene negatively regulated by IRF-1, was increased more than 2-fold." (PMID 27795392, 2016). "In contrast, infection of Cdk2-SN-T160A-NeoR rAAV plus transfection of pX330 CRISPR/Cas9-gCdk2 plasmid resulted in an impressive 44/48 (92%) NeoR colonies containing recombined Cdk2-SN-T160A." (PMID 25586224, 2015). "Of note, detection of phosphorylated CDK1 and CDK2 was reduced during infection compared to control samples." (PMID 24068923, 2013). "Transient activation of CDK2 was shown to occur early in HSV-2 infection at two hours post-infection, and is crucial in early HSV-1 infection." (PMID 20221426, 2010). "Cyclin A, which when complexed with CDK2 initiates the G2/M transition, was upregulated in the presence of a mixed infection of HIGK." (PMID 19689803, 2009). "Both studies also consistently showed a regulation of Cdk2 and Cdk4/6 upon infection of epithelial cells with P. gingivalis." (PMID 19689803, 2009). "Both Cdk2 and Cyclin D were down-regulated in response to infection with P. gingivalis with respect to transcript levels and protein levels." (PMID 19689803, 2009). "To investigate whether YAP6SA stimulates CM division, we collected postnatal mouse hearts after 3 d of AAV9 infection and performed immunofluorescence (IF) to examine the CM cell cycle activity using the cell cycle markers CDK2, pHH3, and cyclin A2." (PMID 41577381, 2026). "Importantly, CDK2 knockdown reduced IFI16 filament formation at later stages of infection (8 hpi) and dampened the induction of cytokines in an IFI16-dependent manner." (PMID 37283074, 2023). "Additionally, using biochemical enrichment, bioinformatics, and mass spectrometry, we identified CDK2 and GSK3β as kinases present at the nuclear periphery during infection and contributing to the IFI16 IDR phosphorylation." (PMID 37283074, 2023). "Lastly, the CDK2 inhibitor, Cdkn3 also accumulated late in infection." (PMID 38107402, 2023). "Inhibition of CDK2 could be used to control neutrophil numbers at the sites of infection or injury, potentially preventing neutrophil-mediated excessive inflammation." (PMID 35873580, 2022). "Analysis of HBV CCC DNA levels in the infected cells three days post-infection showed that both CDK2 inhibitors could decrease CCC DNA formation during infection." (PMID 32226051, 2020). "In addition, CSFV Shimen infection induced cell cycle arrest at the G1 phase, as well as downregulation of cyclin E1 and cyclin-dependent kinase 2 (CDK2)." (PMID 28915564, 2017). "We demonstrated that cyclinD, CDK4, CDK6, cyclinE1 and CDK2 are down-regulated after EV-D68 infection, which could explain the ability of EV-D68 to inhibit the transition from G0/G1 to S phase." (PMID 28229049, 2017). "In contrast, infection of Cdk2-SN-NeoR rAAV plus transfection of pX330 CRISPR/Cas9 plasmid co-expressing a Cdk2 guide strand RNA (gCdk2) that targets a unique sequence between exons 3 and 4 resulted in an impressive 41/48 (85%) NeoR colonies containing recombined Cdk2-SN." (PMID 25586224, 2015). "Based on locus and integration specific PCR assays, infection of RPE cells with only Cdk2-SN-NeoR rAAV (no CRIPSR) resulted in 2/26 (<8%) NeoR colonies containing recombined Cdk2-SN single alleles, and no double alleles." (PMID 25586224, 2015). "We recently found that the potent CDK inhibitor p21, which inhibits repair synthesis, is targeted for degradation during MVM infection, and our earlier work has shown that complete abrogation of CDK2 activity via roscovitine treatment reduced virus replication." (PMID 24415942, 2014). "We investigated whether cyclin EL induction and the increased interaction between cyclin EL and CDK2 in A549 cells after Adwt and Adhz63 infection may promote CDK2 phosphorylation at the specific T160 site." (PMID 23437375, 2013).
infection (continued). "During SVCV infection, cells overexpressing TBK1 showed little CPE; however, CDK2 dramatically counteracted the antiviral capacity of TBK1, as confirmed by virus titer identification." (PMID 41532831, 2026). "After infection with the spring viremia of carp virus (SVCV), fish CDK2 expression significantly increased in tissues and cells." (PMID 41532831, 2026). "Upon siRNA knockdown of CDK2 in IFI16-GFP expressing HFFs, we observed a significant reduction in IFI16 filament formation during infection." (PMID 37283074, 2023). "CDK2 and CCNA2 play vital roles in regulating the eukaryotic cell division cycle, but IAV tries to arrest the cell cycle during infection." (PMID 35019712, 2022). "Ninety-six hours after infection, total RNA was extracted and the transcript levels for LAST, CCND1, CCNE1, CDK2, CDK4 and c-Myc were analyzed by real-time RT-PCR." (PMID 29199958, 2017). "To further confirm our findings, that SAMHD1 phosphorylation is responsible for the efficient productive infection of DCs with HIV-C, we next pre-incubated DCs with the potent CDK2 inhibitor Roscovitine before exposure to virus." (PMID 26121641, 2015). "This hypothesis will be the subject of our future work, including cell cycle synchronization experiments and time-course analyses of CDK2 activity and IFN output during infection." (PMID 41532831, 2026). "Taken together, these results suggest that origin firing during a BKPyV infection uses the canonical kinases Cdc7 and Cdk2, and DDR activation does not prevent these kinases from firing origins as the newly licensed origins are fired prior to DDR activation." (PMID 39636788, 2024). "In cultured VSMCs, treatment with PGE1-OH or infection of Ad-EP4 also significantly upregulated the mRNA levels of genes related to cell proliferation including Ki67, Foxm1, Ccna2, Ccnb1, Ccnd1, Ccnd2, Ccne1, and CDK2." (PMID 36078128, 2022). "Of the tissues evaluated in the present study, gene expression in the HRT was the most severely impacted by infection, with significant decreases in all three cell cycle promoters (CDK1, CDK2 and CDK4) and the largest increase in expression of their inhibitor CDKN1A." (PMID 35189966, 2022). "Cyclin E siRNA studies showed that, in the absence of cyclin E, OAdmCherry infection failed to induce CDK2 phosphorylation in MCF7/pS cells, and that this effect was further increased by palbociclib." (PMID 31100952, 2019). "Following 24 h of MDRV infection, protein expression levels of p10.8, BiP, p-PERK, p-eIF2α, CHOP, cleaved-Caspase12, cleaved-Caspase3 all increased, while expression levels of Cyclin E, CDK2, CDK4 decreased." (PMID 29977231, 2018). "Based on locus and integration-specific PCR, infection of RPE cells with only Cdk2-SN-T160A-NeoR rAAV (no CRIPSR) resulted in 1/19 (5%) NeoR colonies containing recombined Cdk2-SN-T160A single alleles, and no double alleles." (PMID 25586224, 2015). "However, in response to infection, male mice exhibited higher expression levels of CDKN1B, and CTNNB1 (KO, 1A3), TCF4 (1A0, 6A2), TAP1, and TAP2, (1A0), CDKN1A, (1A3, 6A2), MARCO, and MMP12 (1A3), CCND1, CDK2, IRF and MYC (6A2) compared to females." (PMID 32670284, 2020). "Many genes associated with the cell death such as tumour necrosis factor receptor (Tnfrsf1a), inhibitor of kappaB kinase (Ikbkg), kinases (Cd82 and Cdk2), and apoptosis regulator (Bcl2l1 and Birc2) were only up-regulated in WT infection and showed no expression in BM16 infection." (PMID 27634329, 2016). "Indeed in preliminary experiments we have found reduced, but not complete, inactivation of CDK2 activity following infection (Adeyemi and Pintel, unpublished)." (PMID 24415942, 2014). "This was confirmed by detecting cdk2 after THP-1 cells infection with VSV, and it was observed that cdk2 was not upregulated." (PMID 41532831, 2026).
infection (continued). "We investigated the impact of the MAPK family inhibitors Selumetinib (MEK1 and MEK2) and JNK-IN-8 (JNK family), and the impact of CDK family kinase inhibitors Roscovitine (CDK2, CDK5), Dinaciclib (CDK4, CDK6), and the non-specific CDK/Crk during infection (Fig. EV2A,B)." (PMID 38177504, 2024). "Additionally, CDK2 knockdown also led to reduced isg54 and isg56 levels in scrambled-KO HFFs, but not in IFI16-KO HFFs during infection." (PMID 37283074, 2023). "RUVBL2, ADNP, SF3A2, CDK2, PRKDC, and NONO were particularly interesting as the increase in acetylation following SIRT2 inhibition temporally aligned with the time point of maximal interaction with SIRT2 during infection." (PMID 37916830, 2023).
adenocarcinoma (5 papers, 2014 to 2024). A common cancer characterized by the presence of malignant glandular cells. "In line with these dependency data, we observed that NE-like GEMMs and patients with NEPC had significantly higher cdk2 expression when compared with their adenocarcinoma counterparts." (PMID 39113611, 2024).
hematological malignancies (3 papers, 2020 to 2022). "We evaluated fadraciclib, a CDK2/CDK5/CDK9 inhibitor which has successfully completed a First-in-Human Phase I clinical trial, and is continuing clinical development in both solid tumors and hematological malignancies." (PMID 34465787, 2021).
neurodegenerative disease (2 papers, 2018 to 2023). A disorder of the central nervous system characterized by gradual and progressive loss of neural tissue and neurologic function. "Indeed, some of the drugs or their targets, for example, tretinoin targeting RAR genes and GW‐8510 targeting CDK2 and CDK5, were previously linked to neuroprotective functions or neurodegenerative diseases." (PMID 29959820, 2018).
neurological disorders (1 paper, 2022). "However, roscovitine can also inhibit Cdk1, Cdk2, Cdk7, and Cdk9, the low selectivity for Cdk5 reduces its potential as a drug candidate targeting neurological disorders." (PMID 36438186, 2022).
respiratory disease (1 paper, 2011). "A subset of genes co-expressed with AQP4 and associated to respiratory disease were assigned to potential anti-tumorigenic function like CAV1, EDNRB, or SELENBP1, whereas genes more related to pro-tumorigenic function like CDK2, FOXM1, PLK1 or RRM1 were found to be anti-correlated with AQP4." (PMID 21548930, 2011).
CDK2 also shares sentences with these, for which no sentence is quoted: stomach cancer (4 papers); type 2 diabetes (4); breast (3); cardiac hypertrophy (3); diabetic retinopathy (3); metastatic melanoma (3); pituitary tumor (3); astrocytoma (2); hepatitis C (2); Insulin resistance (2); measles (2); myelodysplastic syndrome (2); Nephropathy (2); Parkinson disease (2); periodontitis (2); testicular tumors (2); adrenocortical tumor (1); adult T-cell leukaemias (1); Anaplastic Thyroid Cancer (1); astrocytic tumor (1); B cell lymphoma (1); bladder tumor (1); bladder urothelial carcinoma (1); bone tumors (1); brain cancer (1); cardiovascular disease (1); chronic myeloid leukemia (1); clear cell renal cell carcinoma (1); Cognitive impairment (1); cutaneous T-cell lymphoma (1).
A further 46 diseases each share a sentence with CDK2 in 1 paper.